LANCL2 (LanC like glutathione S-transferase 2)
Description:
Necessary for abscisic acid (ABA) binding on the cell membrane and activation of the ABA signaling pathway in granulocytes.
Synonyms: GPR69B; TASP
Tractability: Antibody: UniProt places it where antibodies can reach, with high confidence; its Gene Ontology location is reachable by antibodies, with high confidence. PROTAC: ubiquitination databases record sites on it; its protein half-life has been measured; a small molecule that binds it is known.
Gene: Protein-coding gene on chromosome 7 (55,365,337 to 55,433,741, forward strand). Ensembl gene ENSG00000132434.
Subcellular location: Nucleus; Cytoplasm; Cell membrane
Subcellular location (Human Protein Atlas): Cytosol; Nucleoplasm
Gene Ontology:
Molecular function: phosphatidylinositol-3-phosphate binding; phosphatidylinositol-4-phosphate binding; phosphatidylinositol-5-phosphate binding; protein binding; ATP binding; GTP binding
Biological process: negative regulation of DNA-templated transcription; positive regulation of abscisic acid-activated signaling pathway; carbohydrate metabolic process; peptide modification
Cellular component: cortical actin cytoskeleton; cytoplasm; cytosol; nucleoplasm; nucleus; plasma membrane
Genetic constraint (gnomAD): Loss-of-function variants: 31 observed, 49.46 expected, observed/expected ratio (o/e) 0.63, 90% interval 0.47 to 0.85. The upper end of that interval is the gene's LOEUF score, 0.85, which puts it in group 3 of 6, group 1 being the genes least tolerant of losing a copy. Missense variants: 517 observed, 528.67 expected, observed/expected ratio (o/e) 0.98, 90% interval 0.91 to 1.05. Synonymous variants: 211 observed, 205.76 expected, observed/expected ratio (o/e) 1.03, 90% interval 0.92 to 1.15.
Homologues: Orthologues: chimpanzee LANCL2 (99% identical), macaque LANCL2 (99% identical), dog LANCL2 (91% identical), guinea pig LANCL2 (90% identical), mouse Lancl2 (89% identical), rabbit LANCL2 (88% identical), rat Lancl2 (82% identical), pig LANCL2 (78% identical), tropical clawed frog lancl2 (75% identical), zebrafish lancl2 (69% identical), Drosophila melanogaster CG2061 (31% identical). Paralogues in human: LANCL1 (51% identical), LANCL3 (31% identical).